CTLA4 (cytotoxic T-lymphocyte associated protein 4)
Diseases named in the same sentence as CTLA4 in open-access papers (continued):
Sharing a sentence is not in itself a finding about the gene and the disease.
cancer (continued). "Immune checkpoint blockade (ICB) is an essential strategy in cancer immunotherapy, targeting inhibitory molecules like PD-1, PD-L1, and CTLA-4 to boost antitumor responses." (PMID 39684701, 2024). "In our study, we investigated the expression patterns of new and old immune examination site receptors and ligands, including PD-1 and CTLA4, as well as 13 immune microenvironment cells in TCGA pan-cancer." (PMID 39120585, 2024). "A research team retrospectively analyzed 1344 phase III clinical trials of advanced cancer treated with anti-PD-1 antibodies and anti-CTLA-4 antibodies." (PMID 38920620, 2024). "The field of cancer immunotherapy has advanced rapidly since the first approvals of monoclonal antibodies targeting CTLA-4 and PD-1." (PMID 38312352, 2024). "These monoclonal antibodies target specific immune checkpoints, such as cytotoxic T-lymphocyte-associated protein 4 (CTLA-4) and programmed cell death protein 1 (PD-1), thereby potentiating immune responses against cancer cells." (PMID 39034999, 2024). "Ipilimumab is a monoclonal antibody that targets CTLA-4, enhancing the immune response against cancer cells." (PMID 38931856, 2024). "The anti‐CTLA‐4 antibodies, such as ipilimumab and tremelimumab, are widely applied as therapeutic agents in clinical trials of different cancers." (PMID 38881673, 2024). "Classical ICIs, such as programmed cell death protein-1 (PD-1), PD-L1, cytotoxic T-lymphocyte-associated antigen 4 (CTLA-4), and lymphocyte activation gene-3 (LAG-3) inhibitors, have been approved for the treatment of various cancers." (PMID 38627681, 2024). "Checkpoint inhibitors, such as anti-PD-1 (pembrolizumab) and anti-CTLA-4, block inhibitory signals that prevent T cells from attacking cancer cells." (PMID 39456771, 2024). "Combination therapy with cancer vaccines and anti-CTLA4 antibodies for malignant tumors has been the subject of numerous clinical trials." (PMID 39302712, 2024). "This differentiation is associated with poor responses to immunotherapy in cancer patients and the upregulated expression of “exhaustion” cell markers such as PD-1, TIM-3, LAG-3, TIGIT, and CTLA-4." (PMID 38727261, 2024). "ICIs against CTLA-4 and PD-L1 have been proposed to be important indicators for both CYTlow and CYThigh cancer patients." (PMID 38612436, 2024). "While ICIs like anti-PD-1 and anti-CTLA-4 mAbs overcome inhibitory signals to unleash T-cell activity against cancer, they also pose a dual role regarding apoptosis regulation." (PMID 38891056, 2024). "Immunotherapies for cancer that target immune checkpoints, such as anti-PD-1/L1 antibodies and CTLA4, have demonstrated clinical efficacy across multiple cancer types." (PMID 38903179, 2024). "Plausibly, the dual blockade of CTLA4 and PD-L1 together with irradiation converges on the cancer regression with abscopal responses." (PMID 38474078, 2024). "Recent research has shown that malignant neoplasms and persistent infections both up regulate CTLA-4, which affects the host immune system." (PMID 38596123, 2024). "Specifically, CYThigh cancer patients exhibited significantly higher levels ofPD-L1 and CTLA-4, among other immune checkpoints, and responded better to ICI therapies." (PMID 38612436, 2024). "As an immunosuppressive checkpoint, targeting CTLA-4 to activate immunity for cancer treatment has been widely studied." (PMID 38459592, 2024). "It is conceivable that anti-PD1/L1 combined with chemotherapy is superior to anti-PD1/L1 with anti-CTLA4 for the treatment of certain cancers." (PMID 38539487, 2024). "Co-inhibitory proteins, such as CTLA-4 and PD-1, bind to their corresponding ligands on cancer cells, resulting in the prevention of cancer-specific T cell activation and the escape of cancer cells from immune surveillance." (PMID 38248769, 2024). "As detailed in the previous section, cancer immunotherapies, including CTLA-4 and PD-1/PD-L1 inhibitors, have shown substantial clinical benefits." (PMID 38732051, 2024).
cancer (continued). "Monoclonal antibodies targeting PD-1/PD-L1 and CTLA4 have greatly enhanced the survival outlook for individuals with cancer." (PMID 39132146, 2024). "Ipilimumab (anti-CTLA-4) constitutes the first checkpoint inhibitor that was approved for cancer treatment, significantly improving the OS of metastatic skin melanoma patients." (PMID 38612436, 2024). "Immunotherapy has revolutionized cancer treatment as evidenced by the discovery and successful clinical application of immune checkpoint blockades (ICBs) targeting CTLA4, PD-1, and PD-L1." (PMID 39436262, 2024). "In 2011, the pioneering anti-CTLA4 antibody, Ipilimumab, was approved as a cancer immune checkpoint blockade (ICB) therapy." (PMID 38592036, 2024). "Many cancers evade the immune response by acting on specific proteins that regulate T-cell differentiation, such as CTLA-4 (cytotoxic T lymphocyte-associated protein 4), PD-1 (programmed cell death 1), and PD-L1 (PD-1 ligand 1)." (PMID 39330321, 2024). "FDA-approved immune checkpoint inhibitors target specific proteins such as PD-1, PD-L1, and CTLA-4 and have shown efficacy in treating various cancers, including cervical, breast, colon, bladder, head, neck, lung, liver cancers, and Hodgkin lymphoma." (PMID 39483536, 2024). "Among them, ICIs, which relieve restrictions on immune cells to recover anti-cancer immunological activity, have produced unprecedented clinical benefits, especially anti-PD-1 and anti-CTLA-4 strategies." (PMID 38402299, 2024). "Immunotherapy has revolutionized cancer treatment, especially with the approval of immune checkpoint inhibitors targeting PD‐L1/CTLA‐4 in BLCA." (PMID 39400959, 2024). "The IPS score is valuable for prediction of cancer patient response to immunotherapy with anti-PD-1 and anti-CTLA-4 treatment." (PMID 38742117, 2024). "In contrast to the well-known immunosuppressive mechanism of PD-1/PD-L1, CTLA-4 inhibitors often enhance immune responses, leading to improved immune cell-mediated killing of cancer cells." (PMID 38294629, 2024). "Previous pre-clinical studies using the TRAMP model revealed the efficacy of anti-CTLA4 therapy following the administration of an irradiated cell-based cancer vaccine in radiation-naïve cancer through the activation of effector T-cell response." (PMID 39199612, 2024). "We recently assessed the impact of combination immune checkpoint blockade on the HIV reservoir in the AMC‐095 study, in which 40 PWH with cancer received nivolumab (anti‐PD‐1) alone (n = 33) or nivolumab and ipilimumab (anti‐CTLA‐4; n = 7)." (PMID 39248154, 2024). "ICIs target immune checkpoint proteins like cytotoxic T-lymphocyte-associated protein 4 (CTLA-4), programmed cell death-1 (PD-1), and programmed cell death-ligand 1 (PD-L1), which cancer cells exploit to evade immune detection." (PMID 38392565, 2024). "ICIs (CTLA-4, PD-1, or PD-L1) are widely used to treat solid tumors, with the aim of utilizing host immunity to combat cancer, making them promising strategies for treating solid tumors." (PMID 39351236, 2024). "Both CTLA-4 and PD-1, common inhibitory checkpoints observed on activated T cells, have been identified as the most reliable targets in cancer treatment." (PMID 39407936, 2024). "Based on our findings, we hypothesize that targeting Tregs, for example, with an anti-CTLA-4 checkpoint inhibitor in biopsy-proven high-risk PanIN could be a useful therapeutic intervention to restore immune surveillance and eventually reverse the condition or prevent progression to invasive cancer." (PMID 38474199, 2024). "Research has demonstrated that anti-CTLA-4 combination therapies, such as Treg depletion, cancer vaccines, and modulation of the gut microbiome, are significantly more effective than CTLA-4 monoclonal antibody (mAB) monotherapy." (PMID 38956700, 2024). "In several cancers inhibition of CTLA-4 with monoclonal antibody get consistent and lasting antitumor responses." (PMID 38234663, 2024).
cancer (continued). "Taken together, our results suggest that the gene expression level of CD74 serves as a potential predictor in multiple cancer types for anti-PD-1/CTLA-4 immunotherapy." (PMID 38280003, 2024). "To date, six drugs targeting PD-1 or its ligand PD-L1 and one drug targeting CTLA-4 have been approved for treating various cancers, with several others in advanced stages of development." (PMID 39407936, 2024). "CTLA-4 is one of the most recognized immune checkpoints and has been widely used in cancer immunotherapy." (PMID 38791528, 2024). "Immune checkpoint inhibitors, specifically anti-PD-1, anti PD-L1, and anti-CTLA4 antibodies, have transformed cancer treatment." (PMID 38541669, 2024). "CTLA-4 and PD-1 blockade therapies have demonstrated significant improvements in survival rates across various cancer types." (PMID 39724285, 2024). "CTLA-4’s complex regulation mechanisms highlight the critical role it plays in immunological responses, including those related to cancer and autoimmune diseases." (PMID 38931856, 2024). "The extensive role of CTLA-4 in negatively regulating the immune response and maintaining homeostasis has made it an interesting target for cancer immunotherapy." (PMID 39346924, 2024). "Cancer cells exerts immune evasion through several mechanisms, including the overexpression of cytotoxic T-lymphocyte antigen 4 (CTLA-4), Programmed death 1 (PD-1), or Lymphocyte-activation gene 3 (LAG-3)." (PMID 38322766, 2024). "Immune checkpoint inhibitors, such as anti-PD-1, PD-L1, and CTLA-4 antibodies, have achieved significant success in the treatment of various cancers." (PMID 38504986, 2024). "Cancer immunotherapy has been experiencing a renaissance since the first regulatory approval of the anti-CTLA-4 antibody ipilimumab in 2011 by the FDA." (PMID 38257366, 2024). "CTLA-4, an immune checkpoint present in regulatory T (Treg) cells and activated T lymphocytes, has limited effectiveness when inhibited for cancer treatment." (PMID 38462628, 2024). "In recent years, leveraging the immune system to treat cancer by inhibiting immune checkpoints such as CTLA4, PD-1, and PD-L1 has resulted in a significant breakthrough in the field of cancer treatment." (PMID 39593745, 2024). "Immunotherapies, particularly immune checkpoint inhibitors (ICIs), such as the anti‐PD‐L1, anti‐PD‐1 and anti‐CTLA4, have revolutionized the treatment of cancer." (PMID 38146591, 2024). "Based on the scRNA-seq results, among the reported relevant immune checkpoint proteins, Prmt9 KD significantly upregulated PD-L1 in cancer cells, although PD-L2 and CTLA-4 were also modestly upregulated." (PMID 38413714, 2024). "Immune checkpoint blockade (ICB) targeting programmed cell death protein 1 (PD-1) and cytotoxic T lymphocyte protein 4 (CTLA-4) can induce remarkable, yet unpredictable, responses across a variety of cancers." (PMID 38429524, 2024). "Inhibitory receptors have been identified in cancers, including but not limited to PD-1, CTLA-4, LAG3, and TIM3, etc.." (PMID 38627727, 2024). "In other cancers, IL-21 blockade was able to drastically reduce B cell activation induced by co-administration of anti-PD-1 and anti-CTLA-4 therapy, highlighting the importance of Tfh cell-secreted effector molecules in cancer immunotherapy." (PMID 38649788, 2024). "Immune checkpoint inhibitors (ICIs) targeting PD-1/PD-L1 and CTLA-4 were the earliest developed, showing remarkable benefits in specific patients and revolutionizing the treatment landscape for numerous cancers." (PMID 38903506, 2024). "We collected 674 samples that received anti‐PD‐1 therapy, anti‐PD‐L1 therapy, anti‐CTLA‐4 therapy, or a combination of different therapies from five cancer types of 14 data sets." (PMID 39429885, 2024). "ICIs, particularly monoclonal antibodies that specifically target CTLA-4 and PD-1/PD-L1, have greatly improved patient outcomes and progressed cancer treatment." (PMID 39318624, 2024).
cancer (continued). "We uncovered a positive association between IL-2RG expression and the prognosis of cancer patients undergoing various immunotherapy treatments, including those involving anti-PD1, anti-PD-L1, and anti-CTLA-4." (PMID 38720389, 2024). "In cancer treatment, inhibitory targeting of CTLA-4 and PD-1/PD-L1 has evolved into a fundamental approach." (PMID 38375475, 2024). "By using a more stringent false discovery rate (t-test: σ/σmax > 0.4, q < 1e-5), the number of concordantly hypermethylated genes in both species was reduced to 28 genes covering a network around cancer/T-cells related genes (e.g., CTLA4, ETS1)." (PMID 39362842, 2024). "Immunotherapy with immune checkpoint inhibitors (ICIs) targeting the PD-1/PD-L1 and CTLA4 axis has transformed clinical outcomes for patients across several cancer histologies and has become an integral part of standard treatment regimens." (PMID 39271499, 2024). "Ipilimumab, a kind of monoclonal antibody, binds to CTLA‐4 and reduces the suppression of CTLs' anti‐cancer activities." (PMID 38571678, 2024). "Among the most prominent forms of immunotherapy are immune checkpoint inhibitors (ICIs), which block proteins (such as PD-1, PD-L1, and CTLA-4) that cancer cells or immune cells use to weaken the immune response, allowing a more robust attack on tumors." (PMID 39518676, 2024). "Most studies support that high levels of PD-L1 and CTLA-4 are present in CYThigh cancer patients, being more sensitive to these therapies." (PMID 38612436, 2024). "Ipilimumab binds to CTLA-4, blocking its action on immune cells, therefore, allowing cancer cells to replicate unchecked." (PMID 38406102, 2024). "The emergence of immune checkpoint therapies, especially those targeting PD-1 and CTLA-4, has revolutionized cancer treatment, and LAG-3 is expected to become an important therapeutic target in oncology." (PMID 39743998, 2024). "Clinical data advocate modulating the microbiota as a promising avenue to enhance cancer immunotherapy effectiveness, especially for CTLA‐4 and PD‐1 immune checkpoint inhibitors." (PMID 38685799, 2024). "The combination of PD-1/PD-L1 and CTLA-4 blockers improves cancer patient survival due to their specific mechanisms." (PMID 39328455, 2024). "Immune checkpoint inhibitors (ICIs) are novel antineoplastic therapies that revolutionized treatment of cancer in 2011 after the approval of anti-cytotoxic T lymphocyte antigen-4 (anti-CTLA-4), ipilimumab, for the treatment of melanoma." (PMID 39201062, 2024). "Immune checkpoint blockade (ICB) has undoubtedly changed the landscape of cancer therapies, with PD-1, CTLA-4, and PD-1/LAG-3 therapies becoming FDA-approved for use in multiple malignancies, leading to improved survival for many patients." (PMID 39199630, 2024). "Although the combination of CTLA-4 and PD-1 mABs proved to be efficacious, it is inadequate for high levels of intratumoral macrophages in advanced stages of cancer." (PMID 38956700, 2024). "In recent years, inhibitors specifically targeting immune checkpoints, such as CTLA4, PD-1, and PD-L1, have gained popularity in anticancer immunotherapy and have demonstrated clinical efficacy in many cancer types." (PMID 38713284, 2024). "Immunotherapy has achieved substantial advancements in the treatment of advanced or late cancer patients, especially with the utilization of anti-CTLA-4 and anti-PD1/anti-PDL1 monoclonal antibodies." (PMID 39228005, 2024). "These inhibitors target the dysfunctional immune system, particularly antibodies such as anti-CTLA4 and anti-PD-1, to induce immune cells to kill cancer cells." (PMID 39185404, 2024). "Exhausted T cells also increase expression of CTLA-4 and are increasingly recognized as arising in cancer." (PMID 39204136, 2024). "The most significant advancement in cancer treatment over the past decade has undoubtedly been the introduction of T cell-targeted immunomodulators that block immune checkpoints like CTLA-4 and PD-1 or PD-L1." (PMID 38743676, 2024).
cancer (continued). "These discoveries imply a strong link between lncRNAs related to CTLA-4 and the onset and progression of cancer." (PMID 39143529, 2024). "In support, DEG analysis revealed the down-regulation of PD1, PD-L1, and CTLA4 in integrinScore-high groups in those cancers." (PMID 39436262, 2024). "By blocking CTLA-4, this therapy enhances T cell activation and proliferation, leading to a more robust immune response against cancer cells." (PMID 38398083, 2024). "These include immune checkpoint inhibitors targeting CTLA-4, PD-1, and PD-L1, therapeutic cancer vaccines like Sipuleucel-T, bi-specific T cell engagers (BiTEs), and chimeric antigen receptor T-cells (CAR-T)." (PMID 39104527, 2024). "Immune checkpoint inhibitors (ICIs) like PD-1 and CTLA-4 inhibitors have revolutionized cancer treatment by targeting receptors that modulate the immune response." (PMID 38541669, 2024). "Downregulation of FOXP3 in cancer Tregs was accompanied by significantly decreased mRNA expression of five out of nine tested exhaustion markers: CTLA-4, Tim-3, PD-1, LAG-3 and TIGIT in the endogenous T cells." (PMID 39234236, 2024). "These agents, such as CTLA-4, PD-1, and PD-L1 mAb, have transformed cancer treatment and are now approved in over 15 different cancers." (PMID 38850359, 2024). "The rate, type, and severity of ICI-induced irAEs depend on the type of cancer, host factors, as well as the therapeutic agent since the immunologic impact of CTLA-4 and PD-1 blockade differs." (PMID 38541099, 2024). "Immunotherapy, particularly immune checkpoint inhibitors like PD-1, PD-L1, and CTLA-4, has revolutionized cancer treatment." (PMID 39590166, 2024). "Combining immune checkpoint inhibitors, specifically nivolumab (anti-PD-1) and ipilimumab (anti-CTLA-4), holds substantial promise in revolutionizing cancer treatment." (PMID 38931856, 2024). "Although using ICBs as mono or combination therapies (e.g. PD-1/PD-L1 and CTLA-4) have shown promising results in a few types of cancers, success requires a deeper understanding of the TME and factors that can be targeted to enhance antitumor immune responses." (PMID 38668817, 2024). "These inhibitors also effectively reduce PD-L1 expression in cancer cells, thereby enhancing the effectiveness of PD-1 or CTLA-4 therapies." (PMID 38693104, 2024). "For these reasons, we used AI in this study to identify anti-CTLA-4 drugs, and we believe that it can also be used to help speed up the discovery of other small-molecule inhibitors of cancer." (PMID 38312352, 2024). "Antibodies targeting CTLA-4 have been promising treatments for numerous cancers, but the mechanistic basis of their anti-tumoral immune-boosting effects is poorly understood." (PMID 38053333, 2024). "Immune checkpoint inhibitors (PD-1, PD-L1, and CTLA-4), developed from a deep understanding of T cell biology, have achieved varying degrees of success in treating many types of cancer." (PMID 39590166, 2024). "A major immune escape mechanism involves inhibiting T-cell activation through interactions between PD-1 on T cells and PD-L1 on cancer cells, as well as between CTLA-4 on T cells and CD80/CD86 molecules on DCs, which are key targets of current immunotherapies." (PMID 39769351, 2024). "Since it was difficult to evaluate cancer cell apoptosis in vivo due to technical difficulty, we examined the effect of anti-CTLA-4 on Hepa1-6 cells in vitro." (PMID 39106430, 2024). "Many studies have shown that the higher the expression of immune checkpoint proteins, such as PD1, PD-L1, and CTLA4, the greater the clinical benefit for patients with carcinoma from ICIs." (PMID 38556542, 2024). "Spatial protein profiling corroborates these findings, revealing significantly decreased CD25+ and FOXP3+ Tregs in infiltrated stroma areas and CTLA4+ cells in both infiltrated stroma and carcinoma areas of GATA6high tumors." (PMID 38733987, 2024).